CASP8AP2 (caspase 8 associated protein 2)
Description:
Participates in TNF-induced blockade of glucocorticoid receptor (GR) transactivation at the nuclear receptor coactivator level, upstream and independently of NF-kappa-B. Suppresses both NCOA2- and NCOA3-induced enhancement of GR transactivation. Involved in TNF-induced activation of NF-kappa-B via a TRAF2-dependent pathway (By similarity). Acts as a downstream mediator for CASP8-induced activation of NF-kappa-B. Required for the activation of CASP8 in FAS-mediated apoptosis. Involved for histone gene transcription and progression through S phase: required for the generation of mature histone mRNAs following the 3' end cleavage of histone pre-mRNAs.
Synonyms: FLASH; KIAA1315; RIP25; CED-4; FLJ11208
Gene: Protein-coding gene on chromosome 6 (89,829,894 to 89,874,436, forward strand). Ensembl gene ENSG00000118412.
Subcellular location: Cytoplasm; Nucleus; Nucleus, PML body; Mitochondrion
Subcellular location (Human Protein Atlas): Nuclear bodies; Nucleoli
Genetic constraint (gnomAD): Loss-of-function variants: 17 observed, 122.03 expected, observed/expected ratio (o/e) 0.14, 90% interval 0.094 to 0.21. The synonymous counts are far from expectation, so gnomAD's model fits this gene poorly and the ratio says little. Missense variants: 1,642 observed, 2,055.7 expected, observed/expected ratio (o/e) 0.8, 90% interval 0.77 to 0.83. Synonymous variants: 588 observed, 705.21 expected, observed/expected ratio (o/e) 0.83, 90% interval 0.78 to 0.89.
Homologues: Orthologues: chimpanzee CASP8AP2 (98% identical), macaque CASP8AP2 (95% identical), dog CASP8AP2 (80% identical), pig CASP8AP2 (78% identical), rabbit CASP8AP2 (77% identical), mouse Casp8ap2 (66% identical), rat Casp8ap2 (65% identical), guinea pig CASP8AP2 (61% identical), tropical clawed frog casp8ap2 (24% identical), zebrafish casp8ap2 (23% identical), Drosophila melanogaster FLASH (7% identical).
Diseases named in the same sentence as CASP8AP2 in open-access papers:
CASP8AP2 is named in the same sentence as 24 diseases in open-access papers, as found by Europe PMC text mining. Sharing a sentence is not in itself a finding about the gene and the disease. The quoted sentences say what the papers report.
acute lymphoblastic leukemia (7 papers, 2011 to 2025). Leukemia with an acute onset, characterized by the presence of lymphoblasts in the bone marrow and the peripheral blood. "Low expression of E2F3a and caspase 8 associated protein 2 (CASP8AP2) are associated with poor prognosis of childhood acute lymphoblastic leukemia (ALL)." (PMID 29568235, 2018). "Hypermethylation was also detected at the promoter region of Caspase 8 associated protein 2 (CASP8AP2) gene in acute lymphoblastic leukemia." (PMID 24172544, 2013).
leukemia (4 papers, 2018 to 2022). A malignant (clonal) hematologic disorder, involving hematopoietic stem cells and characterized by the presence of primitive or atypical myeloid or lymphoid cells in the bone marrow and the blood. "CASP8-associated protein 2 (CASP8AP2) is involved in apoptosis and autophagy and in leukemia." (PMID 36299731, 2022). "In 32 of 33 leukemias the deletion of MAP3K7 also included the adjacent CASP8AP2 gene." (PMID 29914415, 2018). "The following sections summarize the eight top-ranked genes in some of the major drug classes (FLT3, CASP8AP2, L2HGDH, MNT, BAZ2B, MZF1, BEX2, and SMARCA4) that are highly likely to have notable biological significance in leukemia." (PMID 29298978, 2018). "We assume that all three genes located between MAP3K7 and CASP8AP2 (GJA10, BACH2, MIR4464) and a variable number of adjacent genes are co-deleted in these leukemias." (PMID 29914415, 2018).
breast carcinoma (3 papers, 2015 to 2018). "The targeted CAsp8AP2 methylation was also evidenced by bisulfite sequencing Successful targeted DNA methylation increased the methylation and reduced gene expression of Casp8AP2 in both MSCs and the breast cancer cell line MDA-MB-231." (PMID 26464562, 2015).
colorectal cancer (3 papers, 2012 to 2019). A primary or metastatic malignant neoplasm that affects the colon or rectum. "We have identified Caspase-8-Associated protein 2/FLICE-associated huge protein (CASP8AP2/FLASH) as essential for the survival of colorectal cancer cells." (PMID 22216762, 2012). "The observation that the expression levels CASP8AP2/FLASH are the same in normal and colorectal cancer tissue also suggests a role in normal homeostasis for this protein as would be expected if its primary role is in regulating the expression of the replication-dependent histone genes." (PMID 22216762, 2012).
lung carcinoma (1 paper, 2025). "One of the top hits was CASP8AP2 which was previously identified in a CRISPRi screen as an essential viability factor in lung cancer." (PMID 40345583, 2025).
tumor (10 papers, 2017 to 2025). "In addition to many shared regulators, we found that tumor and normal cells are differentially sensitive to loss of the histone genes transcriptional regulator CASP8AP2." (PMID 27929715, 2017). "In order to understand the mechanism behind the differential response of normal and tumor cells, we analyzed the S-phase phenotypes in more detail, using EdU incorporation assays in multiple tumor and normal cells depleted of CASP8AP2." (PMID 27929715, 2017). "In both normal and tumor cells, the depletion of CASP8AP2 alters mainly the expression of replication-dependent histones." (PMID 27929715, 2017). "To determine why normal and tumor cells respond differentially to CASP8AP2 loss, we examined the expression profiles of non-histone genes after CASP8AP2, NPAT and HINFP siRNA treatment." (PMID 27929715, 2017).
cancer (9 papers, 2011 to 2024). A tumor composed of atypical neoplastic, often pleomorphic cells that invade other tissues. "In cancer cells, loss of CASP8AP2 leads to a failure to synthesize sufficient amount of histones in the S-phase of the cell cycle, resulting in slowing of individual replication forks." (PMID 27929715, 2017). "Recently, increasing evidences have confirmed that miR-210 functions as an oncogene in many types of cancers by degrading its targets such as E2F3, Casp8ap2 and ATM." (PMID 28415557, 2017).
infection (3 papers, 2017 to 2022). The state of being infected such as from the introduction of a foreign agent such as serum, vaccine, antigenic substance or organism. "Furthermore, the apoptosis-associated gene, CASP8AP2, exhibited increased expression in clusters A0 and A1, which could potentially explain their proportional decrease in PBMCs after infection." (PMID 35359721, 2022).
CASP8AP2 also shares sentences with these, for which no sentence is quoted: blood tumors (2 papers); colon cancer (2); Ewing sarcoma (2); hepatocellular carcinoma (2); prostate carcinoma (2); acute myeloid leukaemia (1); bladder carcinoma (1); Cerebral ischemia (1); cervical cancer (1); fibrosarcoma (1); glomerulonephritis (1); osteosarcoma (1); ovarian carcinoma (1); pancreatic cancer (1); proliferative glomerulonephritis (1); triple-negative breast carcinoma (1).